MICF (MHC class I polypeptide-related sequence F (pseudogene))
Gene: Transcribed unprocessed pseudogene on chromosome 6 (29,852,363 to 29,852,491, reverse strand). Ensembl gene ENSG00000285799.
Diseases named in the same sentence as MICF in open-access papers:
MICF is named in the same sentence as 2 diseases in open-access papers, as found by Europe PMC text mining. Sharing a sentence is not in itself a finding about the gene and the disease. The quoted sentences say what the papers report.
myocardial infarction (1 paper, 2024). Gross necrosis of the myocardium, as a result of interruption of the blood supply to the area, as in coronary thrombosis. "Taken together, these results suggested that IFN-β secreted by macrophages could block MICF reprogramming after myocardial infarction in mice." (PMID 38530808, 2024).
MICF also shares sentences with these, for which no sentence is quoted: infarction (1 paper).